CD4 (CD4 molecule)
Diseases named in the same sentence as CD4 in open-access papers (continued):
Sharing a sentence is not in itself a finding about the gene and the disease.
tumor (continued). "There was not a significant difference between the percentage of total CD45hi or CD4+ T cells within both the spleen and tumor over time in saline vs. ONP-302-treated mice." (PMID 36059473, 2022). "Human CD4+CD8+ T cells have been suggested to show an anti-tumor capacity that is hampered by the major histocompatibility complex molecules in tumor tissues." (PMID 36091071, 2022). "Deletion of Tgfbr2 in mature CD4+ T cells using Thpok-Cre transgenic mice suppressed tumor outgrowth by relocation of CD4+Tgfbr2−/− T cells from their usual site in the tumor parenchyma to the tumor stroma." (PMID 36382146, 2022). "Compared with those of Fc-treated controls, treatment with HCT-mono-mIL12 variants resulted in significant increases in the populations of CD8+ and CD4+ TILs and their percentages expressing Ki-67, a proliferation marker, in tumor sites." (PMID 36405748, 2022). "Type I IFNs produced by plasmacytoid dendritic cells enhance the cytotoxic activities of natural killer cells and CD8+ CTLs and promote the differentiation of CD4+ helper T cells, resulting in enhanced tumor-specific immune responses." (PMID 35799134, 2022). "This assertion was further supported by the cytokine analysis, wherein we observed reduced IL1β expression in CD4+T cell obtained from tumor, lungs and peripheral blood." (PMID 35741331, 2022). "Among various immune subsets in TME, T cell subsets such as cytotoxic CD8+ T cells, helper CD4+ T cells, and regulatory CD4+ T cells are recognized as key components in the anti-tumor immune response." (PMID 36237314, 2022). "Tumor-infiltrating and circulating CD4 + cytotoxic T lymphocytes (defined as CD4 + T cells with direct lytic activity via expression of perforin and granzyme) have been proven independent prognostic markers of overall survival in many tumors types." (PMID 35606813, 2022). "Infiltration of immune cells involved in tumour elimination (CD8 + T cells, CD4 + T cells and plasma cells) were significantly lower in metastasis compared to primary tumour." (PMID 35904677, 2022). "The previous concept defines the role of CD4+ T cells in anti-tumour immunity as indirect, mainly through Th cells to support CD8+ T cell-mediated tumour killing or Tregs to limit this class response." (PMID 36159866, 2022). "We found that after TDO2 inhibition, in the proximal region from the tumor nests (<20 μm), the proportions of Tregs (Foxp3+CD4+) in CD4+ T cells and exhausted CD8+ T cells (TIM-3+CD8+) in CD8+ T cells were significantly reduced (P < 0.05)." (PMID 35972800, 2022). "The results showed that the low-risk group had many anti-tumor cells, such as CD8+, CD4+, and activated NK cells." (PMID 36275774, 2022). "We observed that ESCC patients with positive TLSs tended to be surrounded by more CD45+ leukocytes, as well as a higher number of tumor‐infiltrating CD4+ T cells, CD8+ T cells CD20+ B cells, and CD11c+ DCs." (PMID 35711130, 2022). "The incorporation of CD4+ TCR-Ts into tumor immunotherapy is expected to present several advantages." (PMID 35928827, 2022). "CD4+ T cells were equally distributed throughout the stroma but significantly less present in the tumor nests." (PMID 35954489, 2022). "An imbalance of CD8+ cytotoxic and CD4+ helper/regulatory T cells in the tumor-infiltrating lymphocyte (TIL) population in surgically treated NSCLCs was assessed to be a prognostic indicator after surgery." (PMID 35669251, 2022). "Cytolytic activity is also seen when tumor antigens are presented restrictively on MHC class II molecules for tandem antigen recognition between CD4+ T-cell TCR and MHC class II molecule." (PMID 35890342, 2022). "The results suggested SCNAs, especially arm-level gain and high amplification, have a differential effect on tumor infiltrating immune cells including B cells, CD4+ T cells, CD8+ T cells, macrophages, neutrophils, and dendritic cells." (PMID 36046250, 2022).
tumor (continued). "According to the Tumor Immune Estimation Resource (TIMER) database, our prognostic signature was significantly associated with tumor-infiltrating B cells, CD4 T cells, dendritic cells, macrophages and neutrophils." (PMID 36185203, 2022). "Two subtypes of helper CD4+ T cells are usually found in largest numbers in close proximity to tumor cells: CD4+ Th2 subtype, which favors the proliferation of B cells, and CD4+CD25+FOXP3+ subtype, known as regulatory T cells (Tregs)." (PMID 35327381, 2022). "By contrast, the role of CD4+ T cells, particularly in the context of tumor metastasis, requires further delineation." (PMID 35784297, 2022). "CD8+ T cells were closer to tumor cells than CD4+ T cells, both in the TC and IM, and CD4+ T cells and CD8+ T cells in TC were farther from tumor cells than in the IM." (PMID 36685566, 2022). "Regulatory T cells (Treg) are an immunosuppressive subgroup of CD4+ T cells, which impair the immune monitoring against cancer and lead to tumor progression." (PMID 35222443, 2022). "Among T cells, immune cells called cytotoxic CD8+ T cells can directly kill tumor cells, while effector CD4+ T cells can activate immune system by sensitizing dendritic cells or other pro-inflammatory myeloid cells." (PMID 36168615, 2022). "To analyze the curative effect of FFCT during CRC treatment, we tested the tumor volume and assessed the T cells (CD4+CD8+) in the blood, spleen, and tumor using a CRC mouse model." (PMID 35694271, 2022). "CD56 positive NKTCL had significantly higher proportion of resting NK cells, activated NK cells, and activated CD8+ and CD4+ T cells in the tumor microenvironment." (PMID 35371002, 2022). "We observed a trend toward increase in CD4 + T cells in tumor following eftozanermin alfa treatment." (PMID 35467243, 2022). "Tumor samples showed significantly higher infiltration abundance of activated memory CD4 T cells, naive B cells, macrophages, and eosinophils, while normal samples showed significantly higher infiltration abundance of plasma cells and resting mast cells." (PMID 35677557, 2022). "The high levels of CD3+CD4+CD279+, CD3+CD8+CD45RO+CD62L+T lymphocytes and tumor mutational burden (TMB) were associated with good efficacy of the combination therapy (P=0.03, P<0.01 and P=0.03)." (PMID 35874743, 2022). "For example, baseline levels of CD4+/CD8+ T cells, macrophage M1, and NK cells, and baseline levels of inflammatory cytokines in tumor invasion have been associated with immune responses." (PMID 35281520, 2022). "Despite evidence of the necessity of cytotoxic CD8+ responses for tumor clearance, there is growing evidence that CD4+ T cells are also necessary for clearing and controlling tumor growth." (PMID 35214655, 2022). "The miR-106a-5p miRNA is highly interconnected with the CD4+ T-cells regulation and works as a tumor suppressor by regulating the VEGFA gene." (PMID 36016137, 2022). "M-MDSC and PMN-MDSC which belong to the innate immune system are the main members of tumor immune tolerance, while CD4+ T cells and CD8+ T cells play an important role in antitumor immunity." (PMID 36394035, 2022). "Here, we show that propranolol treatment resulted in an increased number of tumor infiltrating T cells, with a more prominent effect on CD4 + T cells." (PMID 35017664, 2022). "Although the implanted PyMtOvatg TslprKO tumor (donor tumor) had a high histological grade, recipient mice in the Tslptg TslprKO + WT CD4+ T cell (test) group developed low-grade tumors (P = 0.0005)." (PMID 35657353, 2022). "To directly address the result, we performed immunohistochemistry (IHC) of T-cell marker CD8+ and CD4+ to evaluate tumor-infiltration lymphocytes (IT-TILs) in FFPE tumor tissue, from patients received XELOX therapy or combined with anti-HER2 therapy." (PMID 36175412, 2022).
tumor (continued). "The carrier-free UA NPs exhibited the improved immunostimulatory activity of TNF-α, IL-6, and IFN-β in vitro and inhibited tumor growth with significant activation of CD4+ T cells in vivo, revealing their great potential for cancer immunotherapy." (PMID 36015215, 2022). "Preclinical studies have shown that lymphocytes that infiltrate the tumor as a result of thermal ablation are predominantly CD4+ and CD8+ T cells." (PMID 36569954, 2022). "The infiltration of CD4+/CD8+ T cells in the tumor stroma is closely related to the prognosis and survival rate of tumor patients." (PMID 36090994, 2022). "Tumor-infiltrating lymphocytes (TILs) are represented by CD4+ T helper (Th), CD8+ T cytotoxic (Tc), and regulatory CD4+CD25+FoxP3+ T-cells (Tregs)." (PMID 35269652, 2022). "A linear regression analysis of the SGR with human, and more specifically T cell populations, confirmed the strongest correlation of CD4+ T cells with reduced tumor growth." (PMID 36419897, 2022). "Treatment with unmodified HCT negligibly induced the tumor infiltration of CD4+ and CD8+ T cells, whereas HCT-mono-mIL12 treatment triggered tumor infiltration of those cells." (PMID 36405748, 2022). "CD4+ FoxP3+ regulatory T (Treg) cells promote tumor growth by inhibiting anti-tumor immune responses and cancer immune surveillance." (PMID 34423375, 2022). "The T cell receptor repertoire of the PD-1+ICOS+ CD4+ Th TILs was oligoclonal, with T cell clones expanded in the tumor, but present at low frequencies in the periphery." (PMID 35439168, 2022). "The TCRB clones were from 27.3% ± 27.4% to 46.4% ± 31.0% after ablation (P = 0.024), the transcription levels of granase A and CD11c in CD4+ T cells were also significantly increased in tumor tissues." (PMID 36131929, 2022). "Subsequently, activated CD8+T cells and CD4+T cells are recruited to the TME by the chemokine gradient of CXCL9, CXCL10, and CXCL11 generated by DCs and tumor-associated stroma." (PMID 36003368, 2022). "Deficiency of CCR1 impaired the accumulation of CD11C+, CD4+ and CD8+ cells in tumors, indicating that ECI301 augmented tumor-specific immune responses through CCR1-mediated DC accumulation in tumor." (PMID 36505437, 2022). "Although CD4+ T-cell adoptive transfer alone had considerable therapeutic efficacy, the combination of CD4+ T-cell adoptive transfer and anti-PD-L1 exhibited additional effects in delaying tumor growth." (PMID 35784297, 2022). "For example, activated CD8+T cells directly exert cytotoxic effects on tumor cells, and activated CD4+ T helper 1 (Th1) cells activate macrophages and NK cells by secreting IFN-γ, which promotes anti-tumor effects." (PMID 35897036, 2022). "The therapy also resulted in a significant reduction in MDSCs, the activation and maturation of DCs, and the polarization of M1 macrophage, which are essential for CD4+ T cell-mediated, adaptive, and durable anti-tumor immunity." (PMID 35327361, 2022). "Taken together, our results demonstrate the significant clonal expansion of CD8+ and CD4+ cytotoxic T cells, suggesting that these populations both have encountered tumor antigens." (PMID 35831288, 2022). "The biochemical features of the tumor stromal proteomes were characterized as enrichment of CD4+ and CD8+ T cells, upregulated pathways of antigen presentation, and enhancement of immune signal interactions." (PMID 35433435, 2022). "The role of CD4+ T-cell subsets in CLL is far from being completely understood, but the collective evidence indicates that CD4+ T cells overall are tumor-promoting." (PMID 36266281, 2022). "Compelling evidence has demonstrated the prognostic value of TILs, especially in TNBC where the CD4/CD8 ratio at the tumor-host interface significantly correlates to overall survival essential for both tumor size and nodal status." (PMID 35236356, 2022). "CpG+OVA+PTX+CQ-N/A showed high cytotoxicity against 4T1 cells and significantly improved the levels of CD8+ and CD4+ T cells at the tumor site." (PMID 36303207, 2022).
tumor (continued). "Supporting this view, we observed that the skewing in CD4/CD8 ratio was more prominent within the tumor area than in the extratumoral area." (PMID 34165864, 2022). "In the tumor, CD4+ and PD1+ CD4+ T cells positively associated with monocytic MDSCs, regardless of PD-L1 status, which was not changed by SAR131675 treatment." (PMID 35681695, 2022). "PD-1+ CD4+ T cells and PD-L1+ tumour cells are associated with inflamed—stroma restricted subtypes, whilst PD-L1+ CD8+ T cells and PD-1+ tumour cells dominate in the inflamed—stromal and intratumoural subtype." (PMID 36139665, 2022). "Blocking LAG-3 activity and anti-PD-1 or PD-L1 in tumor cells has dual inhibitory effects, including inhibiting Treg activity, promoting DC maturation, and rescuing dysfunctional CD4+/CD8+ T cells." (PMID 35958563, 2022). "Our study showed that polyfunctional Th1-dominant CD4+ T cells were induced after cryo-thermal therapy to effectively control distant tumor metastasis." (PMID 35874660, 2022). "Specifically, they favor the tumor-promoting function of CD4+ T helper 2 lymphocytes over the tumor-protective T helper 1 response and directly reduce the activation of CD8+ cytotoxic T cells and natural killer (NK) cells." (PMID 36225934, 2022). "Its anti-tumor function was mediated by induced CD4+ CD25+ lymphocytes which elicit transplantable protection in mice." (PMID 36144329, 2022). "The higher levels of tumor-infiltrating macrophages, myeloid dendritic cells, neutrophils, and CD4+ T cells with high TRPV4 expression were significantly associated with shorter survival." (PMID 35813831, 2022). "Different studies have demonstrated that PARP inhibition up-regulates intra-tumor infiltration by both CD4+ and CD8+ T cell subsets." (PMID 36428727, 2022). "It has been shown that DC infiltration in colorectal cancer (CRC) correlated with other tumor-infiltrating CD4+ and CD8+ T cells and that LS patients had elevated mucosal T-cell infiltration even in the absence of cancer." (PMID 36275666, 2022). "When allograft tumors were digested into single cells and analyzed by FCM, however, we found that VPS9D1-AS1 OE prevented CD4/8+ T cell from infiltrating into the tumor tissue." (PMID 36458816, 2022). "CD4+ cells (CD4 Tem, CD4 Treg, and CD4 proliferating) and dnT-cells (dnT and dnT proliferating) showed lower immune score but higher tumor purity compared to CD8 T-cells and NKT." (PMID 35464471, 2022). "An examination of immune cell subsets within spleens revealed that saline-treated mice bearing 4T1 tumors possessed slight increases in the number of CD4+ T cells and B cells and a dramatic increase in CD11b+ myeloid cells, compared to tumor naïve mice." (PMID 36230591, 2022). "Due to the correlative nature of data presented here, it is also conceivable that combined high activin expression and CD4+ T-cell infiltration a marker for a yet to specify tumor subtype." (PMID 36064338, 2022). "It was observed that simultaneous blockage of LAG-3 activity and anti-PD-1 or PD-L1 in tumor cells has dual inhibitory effects, including inhibiting Treg activity, promoting dendritic cells (DCs) maturation, and rescuing dysfunctional CD4+/CD8+ T cells." (PMID 35958563, 2022). "The combination treatment increased the percentage of tumor-infiltrating CD4+, CD8+ T lymphocytes, and CD11c+ dendritic cells compared to X-ray irradiation alone." (PMID 36238646, 2022). "TACE combined with various ablation therapies or immunotherapy for the treatment of PHC can also increase the body’s anti-tumor ability, mainly manifested as CD4+, CD4+/CD8+, NK cell levels increasing, CD8+ and Treg cell level decreasing, etc.." (PMID 35965593, 2022). "Compared with the complement score-low cohort, although fewer CD4+ T cells infiltrated in the tumor microenvironment, the tumor-killing cells including CD8+ T cells and NK cells were observed to be abundant in complement score-high samples." (PMID 35929594, 2022).
tumor (continued). "Cluster 2 expressed a higher level of interferon-gamma (IFN-γ) than did the other CD4+CXCL13+ clusters, indicating that this type of CD4 T cells has a potential role in killing tumor cells." (PMID 36357424, 2022). "With a combination of in vivo and in vitro approaches, we show that B7x expands tumor-infiltrating Treg populations by inducing the expression of the Treg-specific transcription factor Foxp3 in conventional CD4+ T cells and converting them into Tregs." (PMID 35523809, 2022). "The HER2-DC1 i.t. combined with anti-HER2 antibodies treatment group had a higher number of tumor infiltrating CD4+ T cells, compared with the HER2-DC1 s.c. combined with anti-HER2 antibodies treatment group." (PMID 35710296, 2022). "Our group has previously shown that there is a selective loss of CD4+ T cells due to a buildup of linoleic acid within mitochondria which impaired the efficacy of CD4+ T-dependent tumor vaccination against liver tumors in mice." (PMID 35198900, 2022). "In contrast, cytokines produced by T helper-17 cells (Th-17), which are a subpopulation of CD4+-helper T-lymphocytes, demonstrate tumorigenic effects, and tumor infiltration with Th-17 cells adversely affecting the prognosis in CRC." (PMID 36422171, 2022). "Immunotherapy targets two major populations of lymphocytes: CD8 T cells, which directly kill tumor cells, and CD4 T cells, which provide help to CD8 T cells, the role of which in clinical responsiveness to immunotherapy has been less explored." (PMID 35954341, 2022). "In most tumors, SPA17was positively associated with the infiltration of MDSC, CD4+ T cells, progenitors of lymphoid, and CD8+ T cells, suggesting that SPA17 was likely to affect tumor development and prognosis by impacting the tumor microenvironment." (PMID 35592314, 2022). "Y9 showed anti-tumor responses in syngeneic mouse models with several mouse cancer cell-lines indicated by CD4+ and CD8+ T-cell expansion, with increased functionality of CD8+ Teffs, downregulation of memTNF and reduced tumor size." (PMID 35681583, 2022). "We then investigated the correlations between CD4+ Treg subsets with CD4+ T cells expressing different ICs, based on tumor stages." (PMID 36146549, 2022). "In this study, we investigated any potential correlations between frequencies of different Treg subsets with CD4+ T cell expressing different immune checkpoints according to the tumor staging." (PMID 36146549, 2022). "In CT26.WT tumor model, at 48 hours after BGB-A1217 treatment, the intra-tumor Treg frequencies in TILs were significantly decreased, while CD4+ effector T cell and CD8+ T cell populations remained unchanged." (PMID 35273608, 2022). "CD8+ T cells are outnumbered by CD4+ T cells in the tumor microenvironment (TME) of CHL, have follicular helper T-cell (Tfh)-like features, and are suggested to possess decreased cytotoxic function." (PMID 35741318, 2022). "At the immune cell level, lymphocytes such as NK, CD8+, and CD4+ helper T cells, and pro-inflammatory macrophage subtype M1 and DCs elicit an anti-tumor response while MDSCs and Tregs impede tumor immunity." (PMID 35327456, 2022). "CD4+ T cells are reported to play pivotal roles in fighting cancer progression via cytolytic activity or tumor microenvironment modulation." (PMID 36005179, 2022). "Recently, CD19 + tumor-infiltrating B-cells were identified as an independent favorable prognostic factor in MIBC and serve as antigen-presenting cells to activate CD4 + T cell in the tumor microenvironment." (PMID 35027623, 2022). "In tumor immunity, CD4+CD25+ Treg cells inhibit anti-tumor immunity and correlate with decreased patient survival." (PMID 36012586, 2022). "After NACT, mostly with cisplatin, there was a significant decrease in Ki67 and PD-L1 expression specifically on tumor cells, whereas a significant increase in CD4+, CD8+, CD20+, CD56+, and PD-1+ cells was observed in >50% of the patients." (PMID 35566403, 2022).